NPM1 (nucleophosmin 1)
Diseases named in the same sentence as NPM1 in open-access papers (continued):
Sharing a sentence is not in itself a finding about the gene and the disease.
cervical cancer (5 papers, 2015 to 2025). A primary or metastatic malignant neoplasm involving the cervix. "Interestingly, our quantitative acetylproteomic results indicated that AMPK activation via metformin treatment significantly downregulated the acetylation levels at five lysine sites of NPM1 (K248, K202, K154, K229, and K141) in cervical cancer." (PMID 38831454, 2024). "The LTM pathway, which regulates immune cell trafficking across the endothelial barrier, is disrupted in HPV-positive cervical cancer due to the reduced expression of key genes such as HSPA5, CTNNB1, and NPM1." (PMID 41465546, 2025). "This study provides novel insights into HPV-driven immune evasion in cervical cancer, identifying key immune-related hub genes, including HSPA5, CTNNB1, and NPM1, which are downregulated in HPV-positive tumors." (PMID 41465546, 2025). "Although the identified immune-related hub genes (HSP90AA1, CTNNB1, NPM1, HSPA5, and HIF1A) were significantly downregulated in HPV-positive cervical cancer, none of them demonstrated a statistically significant correlation with overall survival in the TCGA-CESC cohort." (PMID 41465546, 2025).
lymph node metastasis (5 papers, 2012 to 2025). "Statistical analysis showed a high expression of NPM1 correlated with lymph node metastasis (P = 0.0003), indicating an association between NPM1 in tumorigenesis and cancer metastasis." (PMID 22631075, 2012). "We observed a strong positive correlation between NPM1 protein levels and lymph node metastasis." (PMID 37251542, 2023).
monocytic leukemia (5 papers, 2011 to 2025). "A possible molecular mechanism linking VEN with NPM1-mutated AML derives from studies in the human monocytic leukemia cell line THP-1 harboring the NPM1 mutation." (PMID 41030943, 2025). "Studies on the human monocytic leukaemia cell line THP-1 with NPM1 mutation reveal an increase in sensitivity to chemotherapy drugs through suppressing NF-κB activity and BCL-2/BAX expression, which is pertinent to the efficacy of venetoclax seen in NPM1-mutated AML." (PMID 36834572, 2023). "Similarly, NPM1-mutated chronic myelomonocytic leukaemia (CMML) cases often carry a normal karyotype and tend to evolve rapidly to AML, especially those with high NPM1 mutation allelic burden." (PMID 33879827, 2021). "THP-1 cells derived from human monocytic leukemia were stably transfected with the recombinant plasmids expressing NPM1-mA, NPM1-wt or empty vector." (PMID 27669739, 2016).
thyroid cancer (5 papers, 2007 to 2023). "NPM1 overexpression has also been reported in thyroid cancer, with thyroid cancer cell lines showing NPM1 mislocalization in the absence of the mutations observed in AML patients." (PMID 27553022, 2016).
triple-negative breast carcinoma (5 papers, 2020 to 2025). An invasive breast carcinoma which is negative for expression of estrogen receptor (ER), progesterone receptor (PR), and human epidermal growth factor receptor 2 (HER2). "It is reported that the PARP1 inhibitor Olaparib can promotes the binding of the transcription factor nuclear phosphoprotein (NPM1) to the PD-L1 promoter in triple-negative breast cancer cells,thereby activating PD-L1 transcription." (PMID 40406122, 2025).
astrocytoma (4 papers, 2015 to 2018). "NPM1 displayed increased staining in grade III and IV astrocytomas, whereas grade II astrocytomas presented NPM1 levels similar to grade I and adjacent near normal tissue." (PMID 26559910, 2015).
autoimmune disease (4 papers, 2005 to 2022). A disorder resulting from loss of function or tissue destruction of an organ or multiple organs, arising from humoral or cellular immune responses of the individual to their own tissue constituents. "As a control group, sera from patients with SLE which is an autoimmune disease were also detected for the presence of anti-NPM1 antibodies." (PMID 25779011, 2015). "However, it is interesting to note that they contain genes associated with disease in humans and dogs including epilepsy (KCNQ5), cancer (NPM1, FGR), and autoimmune disease (IL6)." (PMID 22022279, 2011). "The data suggested that anti-NPM1 autoantibodies are not related to autoimmune diseases such as SLE and other chronic liver diseases, and these antibodies may have close relevance to HCC." (PMID 25779011, 2015).
breast tumor (4 papers, 2012 to 2023). "A potential link between DNA replication and repair genes and in vivo invasion is also evident, with genes such as nucleolin (NCL) and nucleophosmin (NPM1) greatly upregulated in the migratory breast tumor cells." (PMID 23113900, 2012).
colon adenocarcinoma (4 papers, 2021 to 2026). "In order to verify this presumption, we examined the levels of p-NPM1 (Thr199) in tumor tissues from colon adenocarcinoma (CA) patients with different BRAF mutational statuses using immunohistochemistry." (PMID 34201061, 2021). "We reveal an increased abundance and activity of nucleophosmin (NPM1) in BRAFV600E-mutated CC in vitro, in silico and in tumor tissues from colon adenocarcinoma patients and demonstrate the roles of NPM1 and its interaction partner c-Myc in conveying the resistance to vemurafenib." (PMID 34201061, 2021). "Importantly, we detected significantly stronger nuclear and, in particular, cytoplasmic staining of phospho-NPM1 (Thr199) in tumor tissue specimens from BRAFV600E-mutated in comparison with KRAS mutant/BRAF wild-type and double wild-type KRAS/BRAF colonic adenocarcinomas using immunohistochemistry." (PMID 34201061, 2021). "Indeed, NPM1 is significantly overexpressed in many human cancers compared to adjacent normal tissues, but the strongest increase is within colon adenocarcinoma (COAD) and rectal adenocarcinoma (READ)." (PMID 41413654, 2026). "NPM1 mRNA abundance was also significantly reduced in patients with high-grade colon adenocarcinoma (COAD; stages III and IV), compared to those with low-grade COAD (stages I and II)." (PMID 39103576, 2024).
dyskeratosis congenita (4 papers, 2020 to 2023). Dyskeratosis congenita (DC) is a rare ectodermal dysplasia that often presents with the classic triad of nail dysplasia, skin pigmentary changes, and oral leukoplakia associated with a high risk of bone marrow failure (BMF) and cancer. "The very recent discovery of novel mutations in the NPM1 central domain that cause dyskeratosis congenita is a very good example of this line of thinking and demonstrates that NPM1 research, after more than 30 years from its discovery, is still very lively." (PMID 32664415, 2020). "In the same study with NPM1, it was also reported that dyskeratosis congenita patient cells with NPM1 D178H mutation resulted in reduced 2’-O-Me at specific sites and decreased IRES-dependent translation without changes in nucleolar localization of NPM1 D178H57." (PMID 36806717, 2023). "In a recent work by Nachmani and colleagues, germline mutations of the npm1 gene have been associated with the etiogenesis of the ribosomopathy dyskeratosis congenita: these lesions consist of a missense mutation or an in-frame-deletion within the A3 acidic region of NPM1 (see next paragraph)." (PMID 32664415, 2020). "Interestingly enough, the same study identified two novel germline mutations in the NPM1 gene in patients suffering from dyskeratosis congenita, and thus linked impaired 2′-O-Me at multiple levels to this ribosomopathy, characterized by bone marrow failure and associated symptoms." (PMID 32664415, 2020). "In the same study, Nachmani and colleagues also identified two NPM1 mutations, NPM1D178H and NPM1D180del, in patients with Dyskeratosis Congenita (DC), where causative mutations could not have been identified." (PMID 34440717, 2021).
HIV-1 infection (4 papers, 2013 to 2024). The type species of lentivirus and the etiologic agent of acquired immunodeficiency syndrome (AIDS). "It has also been reported that human immunodeficiency virus type 1 (HIV-1) infection induces acetylation of NPM1, which is critical for the nuclear localization of Tat as well as Tat-mediated viral gene transcription." (PMID 38394330, 2024). "Inhibition of Aurora A or Aurora B kinases that phosphorylate NPM1 on Ser-125 residue inhibited HIV-1, further supporting the role of NPM1 in HIV-1 infection." (PMID 36563749, 2023). "These include host cell co-factor proteins that facilitate HIV-1 infection, such as BANF1 (O75531), importin (O95373), NPM1 (P06748), SNW domain-containing protein 1 (Q13573), and PCBP1 (Q15365)." (PMID 36325020, 2022).
influenza (4 papers, 2013 to 2021). An acute viral infection of the respiratory tract, occurring in isolated cases, in epidemics, or in pandemics; it is caused by serologically different strains of viruses (influenzaviruses) designated A, B, and C, has a 3-day incubation period, and usually lasts for 3 to 10 days. "Although the NpM1 sequences of the MVA, Fowlpox recombinants and challenge virus were not homologous, these are highly conserved internal influenza antigens (example 98% homology for NP and 100% for M1 protein)." (PMID 25450002, 2015).
liver cirrhosis (4 papers, 2007 to 2023). "One of the 3 NPM1-positive patients needed venetoclax discontinuation due to diagnosis of decompensated liver cirrhosis after the fifth cycle of venectoclax-azacitidine, continuing with HMA only." (PMID 37051529, 2023). "No significant prognostic associations were found among the other characteristics including age, HBV status, ALT, liver cirrhosis, tumor size and multinodular of NPM1 for OS or TTR." (PMID 28874807, 2017). "The prevalence of autoantibodies against NPM1 was 22.4% (17/76) in HCC, which was significantly higher than that in sera from patients with liver cirrhosis (LC), chronic hepatitis (CH) and systemic lupus erythematosus (SLE) (P<0.01)." (PMID 25779011, 2015).
osteosarcoma (4 papers, 2015 to 2026). A usually aggressive malignant bone-forming mesenchymal neoplasm, predominantly affecting adolescents and young adults. "Five selected NPM1-binders were genetically fused to GFP, and the GFP-tagged binders were transiently expressed in human osteosarcoma (U2OS) cells." (PMID 41394589, 2025). "We co-expressed nucleophosmin-1 (NPM1) fused to SspB (NPM1–mCherry–SspB), together with iLID fused to a multivalent (24-mer ferritin, FTH1) core and a nuclear localization signal (NLS–iLID–GFP–FTH1; GFP, green fluorescent protein), in human osteosarcoma (U2OS) cells." (PMID 38383656, 2024).
pancreatic adenocarcinoma (4 papers, 2018 to 2025). "To further support the association between HMGA1 and NPM1, we performed an mRNA co-expression analysis using two independently curated PDAC datasets (Pancreatic Adenocarcinoma, TCGA, GDC and Pancreatic Ductal Adenocarcinoma, CPTAC, Cell 2021) accessed through cBioPortal." (PMID 41145488, 2025). "Interestingly, NPM1 knockdown attenuated the proliferation and growth of pancreatic adenocarcinoma cells." (PMID 38928092, 2024).
prostate tumor (4 papers, 2014 to 2024). "N6L treatment of prostate tumor cells led to inhibition of NPM1 phosphorylation in conjunction with inhibition of AR activity." (PMID 26993766, 2016). "In order to analyse the impact of NPM1 on prostate tumour cell proliferation, we chose a knockdown strategy and generated LNCaP cell sublines stably expressing control (shScr) or NPM1 specific shRNA (shNPM1)." (PMID 24796332, 2014). "We also show that NPM1 acts as a regulator of the MAPK/ERK pathway and the EGF gene expression, which would explain the change of prostate tumour cell behaviour when NPM1 expression is altered." (PMID 24796332, 2014). "Taken together, these data clearly demonstrate that NPM1 is involved in prostate tumour growth in vitro and in vivo." (PMID 24796332, 2014). "In addition, NPM1 was also found to be overexpressed in colon, breast, gastric, thyroid and prostate tumours." (PMID 38928092, 2024). "Recently, it has been shown that NPM1 could favor migration, invasion and colony forming of prostate tumor cells." (PMID 26993766, 2016). "We now wanted to more specifically investigate whether this deregulation of NPM1 expression may act on prostate tumour cells invasive and migration capacities." (PMID 24796332, 2014). "A contrario, when prostate tumour cells display an increased NPM1 expression, one might then expect that it strongly potentiates tumour growth and aggressiveness." (PMID 24796332, 2014). "The chaperone nucleophosmin (NPM1) is over-expressed in the epithelial compartment of prostate tumours compared to adjacent healthy epithelium and may represent one of the key actors that support the neoplastic phenotype of prostate adenocarcinoma cells." (PMID 24796332, 2014). "Here we show that NPM1 favors prostate tumour cell migration, invasion and colony forming." (PMID 24796332, 2014).
sarcoma (4 papers, 2016 to 2024). A usually aggressive malignant neoplasm of the soft tissue or bone. "Moreover, we found that NPM1 was closely associated with the survival of patients with ES, and high expression of NPM1 in the ES data of GSE17674 and the sarcoma dataset of TCGA often predicted a poor prognosis for patients (p < 0.05)." (PMID 34899858, 2021).
diffuse large B-cell lymphoma (3 papers, 2021 to 2025). "BMF-219, a covalent binding menin inhibitor, is being tested in adult AML and ALL patients with KMT2Ar or NPM1-m, diffuse large B-cell lymphoma (DLBCL), chronic lymphocytic lymphoma (CLL), and multiple myeloma (MM) (COVALENT-101, NCT05153330)." (PMID 39594699, 2024).
head and neck cancer (3 papers, 2018 to 2021). A primary or metastatic malignant neoplasm affecting the head and neck. "The Cancer Genome Atlas database was used to analyze the relationship between NPM1 mRNA expression and the survival rate of patients with head and neck cancer." (PMID 33142921, 2020). "For instance, the protein of ‘NPM1’ shows upregulation in most of the cancers, it was only identified as down-regulated in Head and Neck Cancer." (PMID 29688359, 2018).
kidney cancer (3 papers, 2021). Primary or metastatic malignant neoplasm involving the kidney. "Further, the expression of KPNA2 is positively correlated with NPM1 in kidney cancer." (PMID 34469024, 2021). "To assess whether NPM1 contributes to the proliferation and migration progression of kidney cancer through the regulation of KPNA2, we transfected KPNA2‐targeting siRNA into ACHN cells with forced expression of NPM1." (PMID 34469024, 2021). "Next, in in vitro and vivo analysis, our results indicated that KPNA2 may regulate NPM1 to promote the progression of kidney cancer." (PMID 34469024, 2021). "So, KPNA2 may regulate NPM1 via c‐Myc to promote the proliferation of kidney cancer cells." (PMID 34469024, 2021).
leukocytosis (3 papers, 2011 to 2022). "Groups with higher FLT3–ITD ARs were more frequently female (p = 0.008), had higher leukocytosis (p < 0.001), and more frequently showed the co-occurrence of mutated NPM1 (p < 0.001)." (PMID 36497281, 2022). "In this patient, the diagnosis of de novo AML with mutated NPM1 was made on his first bone marrow biopsy showing 70% CD13, CD33, CD117, HLA-DR(+), and CD34(−) myeloblasts with circulating blasts and marked leukocytosis." (PMID 27752371, 2016). "CR rate was significantly influenced by leukocytosis with a cut-off at WBC>30 G/L (95% CI, 0.14-0.68, OR, 0.3, p=0.01) but not by age, CEBPA, NPM1 or FLT3-ITD mutations." (PMID 22081665, 2011).
myelodysplastic/myeloproliferative neoplasm (3 papers, 2020 to 2025). A category of clonal hematopoietic disorders that have both myelodysplastic and myeloproliferative features at the time of initial presentation. "Though less frequent compared with de novo AML, NPM1 mutations have also been observed in secondary AML (defined as progressing from either MDS or myelodysplastic/myeloproliferative neoplasm (MDS/MPN)) with a variable incidence ranging from 4.5% to 27% of cases." (PMID 35054502, 2022).
ovarian serous cancer (3 papers, 2018 to 2024).
pancreatic ductal adenocarcinoma (3 papers, 2015 to 2025). An infiltrating adenocarcinoma that arises from the epithelial cells of the pancreas. "In this study, we demonstrated that NPM1 expression is up-regulated in pancreatic ductal adenocarcinomas, while elevated expression in tumor tissues may be linked to a poorer prognosis." (PMID 26068981, 2015). "In the present study, we determined the roles of NPM1 in pancreatic ductal adenocarcinoma (PDAC) aerobic glycolysis and of NPM1-FBP1 axis in pancreatic tumorigenesis." (PMID 26068981, 2015).
peripheral T cell lymphoma (3 papers, 2016 to 2021). "In peripheral T-cell lymphomas, ALK rearrangements with NPM1 and other genetic partners are the most common." (PMID 34944796, 2021).
refractory anemia (3 papers, 2014 to 2024). "Among 32 AMLDNMT3A/FLT3/NPM1 cases with FAB classification data, 10 (31%) were M4; 8 (25%) were M5; 6 (19%) were M1; 6 (19%) were M2; 1 (3%) was M0; and, 1 (3%) was refractory anemia with excess blasts in transformation." (PMID 25281355, 2014).
thyroid tumor (3 papers, 2012 to 2018). A benign or malignant neoplasm affecting the thyroid gland. "Nevertheless, the overexpression of NPM1 is found in many types of solid human tumors, including tumors of the thyroid, brain, liver, and prostate." (PMID 23271972, 2012).
adenoma (2 papers, 2017 to 2026). A neoplasm arising from the epithelium. "Remarkably, Npm1 deletion suppressed this rapid adenoma model, extending survival threefold, while tumors again retained NPM1 expression." (PMID 41413654, 2026).